FAM201A (family with sequence similarity 201 member A)
Synonyms: formerly C9orf122
Gene: Long non-coding RNA gene on chromosome 9 (38,620,474 to 38,624,990, forward strand). Ensembl gene ENSG00000204860.
Diseases named in the same sentence as FAM201A in open-access papers:
FAM201A is named in the same sentence as 19 diseases in open-access papers, as found by Europe PMC text mining. Sharing a sentence is not in itself a finding about the gene and the disease. The quoted sentences say what the papers report.
esophageal squamous cell carcinoma (3 papers, 2018 to 2022). Esophageal squamous cell carcinoma (ESCC) is a type of esophageal carcinoma (EC) that can affect any part of the esophagus, but is usually located in the upper or middle third. "In esophageal squamous cell cancer, lncRNA FAM201A was reported to upregulate radioresistance via miR-101/ATM axis." (PMID 35600868, 2022). "Besides, lncRNA FAM201A has also been uncovered as a potential biomarker for radio-resistance in esophageal squamous cell carcinoma (ESCC)." (PMID 33330444, 2020).
osteonecrosis (3 papers, 2018 to 2023). A none disease characterized by death of bone tissue due to a lack of blood supply. "Aside from its role in cancers, a decrease in FAM201A expression has been linked to osteonecrosis of the femoral head." (PMID 37626805, 2023). "In addition to cancers, down-regulation of FAM201A was reported to be associated with Osteonecrosis of the femoral head through bioinformatics analysis and quantitative real-time polymerase chain reaction experiments." (PMID 35410298, 2022).
atrial fibrillation (2 papers, 2022 to 2023). A disorder characterized by an electrocardiographic finding of a supraventricular arrhythmia characterized by the replacement of consistent P waves by rapid oscillations or fibrillatory waves that vary in size, shape and timing and are accompanied by an irregular ventricular response. "This study indicated that the down-regulation of FAM201A could potentially be used as a predictive marker for atrial fibrillation susceptibility." (PMID 37626805, 2023).
cervical cancer (2 papers, 2022 to 2024). A primary or metastatic malignant neoplasm involving the cervix. "Overall, this study showed that FAM201A promoted cervical cancer progression and metastasis by targeting the miR-1271-5p/FLOT1 axis-induced Wnt/β-catenin pathway." (PMID 36226250, 2022). "This study investigated the role of the family with sequence similarity 201-member A (FAM201A), as previously reported oncogenic, in cervical cancer (CC)." (PMID 36226250, 2022). "Moreover, FAM201A drives cervical cancer progression by targeting the miR‐1271‐5p/FLOT1 axis, ultimately activating the Wnt/β‐catenin pathway." (PMID 38827027, 2024).
lung adenocarcinoma (2 papers, 2022 to 2023). A carcinoma that arises from the lung and is characterized by the presence of malignant glandular epithelial cells. "In previous studies related to FAM201A, the expression of FAM201A showed a relatively consistent up-regulation trend in several tumors, including lung adenocarcinoma, triple-negative breast cancer, and hepatic cancer cells." (PMID 37438449, 2023). "Another in vivo experiment showed that high level expression of FAM201A involved in development of lung adenocarcinoma and down-regulation of FAM201A exerted the opposite effect." (PMID 35410298, 2022).
lung carcinoma (2 papers, 2021 to 2022). "Additionally, highly expressed FAM201A was reported to provoke short-term radio-resistance, leading to inferior survival in patients with esophageal squamous cell cancer and nonsmall-cell lung cancer." (PMID 36226250, 2022). "The efficacy of irradiation is also improved by FAM201A knockdown in lung cancer xenografts." (PMID 34298879, 2021). "FAM201A was recently proven to modulate the effect of radiotherapy in lung cancer." (PMID 34298879, 2021). "We detected a unanimous increase in FAM201A expression in all CC in vitro and in vivo samples, which was consistent with the FAM201A expression patterns in TNBC and lung cancer, where FAM201A played oncogenic roles." (PMID 36226250, 2022).
lung squamous cell cancer (2 papers, 2020 to 2022). "LncRNA FAM201A mediates the metastasis of lung squamous cell cancer via regulating ABCE1 expression." (PMID 32976115, 2020). "In patients with lung squamous cell cancer, FAM201A was up-regulated." (PMID 35410298, 2022).
breast carcinoma (1 paper, 2022). "Reduced expression of BLACAT1 in HNSCC; MALAT1, NEAT1 and PVT1 in NPC; FAM201A, PVT1 and LINC00857 in NSCLC; LINC00473, CCAT2and Rpph1 in EC; HOTAIR and LINC00958 in CRC; AFAP1-AS1 and LINC00511 in breast cancer were correlated with radiosensitivity." (PMID 36323697, 2022).
cervical squamous cell carcinoma (1 paper, 2022). A squamous cell carcinoma arising from the cervical epithelium. "According to Gene Expression Profiling Interactive Analysis (GEPIA) based on Cancer Genome Atlas Cervical Squamous Cell Carcinoma and Endocervical Adenocarcinoma (TCGA-CESC) database, FAM201A expression level was higher in CC tissues than that in normal tissues (P < 0.05)." (PMID 36226250, 2022).
gastritis (1 paper, 2023). Inflammation of the stomach. "In this study, we screened 11 important lncRNAs (AFAP1-AS1, MIR155HG, LINC00472, and FAM201A) and mRNAs (CASP10, SLC26A2, TRIB1, BMP2K, SCAMP1, TNKS1BP1, and MBOAT2) according to the gene expression profiles of gastric epithelial tissues in different stages of Hp infection-induced gastritis." (PMID 37249580, 2023).
neuroblastoma (1 paper, 2023). Neuroblastoma (NB) is the most common solid, extracranial childhood tumor. "The long non-coding RNA FAM201A encodes a short peptide NBASP that suppresses neuroblastoma carcinogenesis by down-regulating FABP5 to inactivate the MAPK pathway." (PMID 37438449, 2023).
non-small cell lung carcinoma (1 paper, 2022). A group of at least three distinct histological types of lung cancer, including non-small cell squamous cell carcinoma, adenocarcinoma, and large cell carcinoma. "In tissues from non-small cell lung cancer patients, elevated expression level of FAM201A was detected related to radioresistance." (PMID 35410298, 2022).
prostate carcinoma (1 paper, 2021). A carcinoma that arises from epithelial cells of the prostate gland. "Prostate cancer samples with higher level of FAM201A exhibited significantly lower level of “TGF-β response” activity (P = 2.7E-12)." (PMID 33665192, 2021).
cancer (8 papers, 2018 to 2023). A tumor composed of atypical neoplastic, often pleomorphic cells that invade other tissues. "Cell function assay demonstrated that depletion of ORF1 in FAM201A resulted in loss of anti-cancer effect of FAM201A by CCK8, colony formation and transwell assays." (PMID 37438449, 2023). "FAM201A, a family of long non-coding RNA, was previously demonstrated to be implicated in various diseases, particularly cancers." (PMID 37626805, 2023). "Numerous lncRNAs, including FAM201A, have been confirmed to function as an oncogene in multiple types of human cancers by suppressing malignant phenotypes such as cancer cell proliferation, migration, invasion, and in vivo tumorigenesis." (PMID 36226250, 2022). "FAM201A was demonstrated to be involved in various diseases previously, especially cancers." (PMID 35410298, 2022). "Interactive analyses have identified FAM201A as a key regulator in cancer progression in a lncRNA-miRNA-mRNA competing endogenous RNA (ceRNA) network, via which FAM201A was found to indirectly regulate the expression of messenger RNA (mRNA) by sponging its targeted microRNAs (miRNAs)." (PMID 36226250, 2022). "In conclusion, the present study revealed that lncRNA FAM201A may be a potential biomarker for predicting radiosensitivity and prognosis, as well as a therapeutic target for enhancing cancer radiosensitivity in ESCC." (PMID 30574162, 2018). "Functional analyses of FAM201A-miRNA-mRNA ceRNA networks indicated that FAM201A could sponge miRNAs and unleash mRNAs from the binding of FAM201A, with miRNAs critical for the promotion of cancer progression." (PMID 36226250, 2022).
tumor (5 papers, 2018 to 2025). "Here, we found that FAM201A was low expressed in NB and a variety of gain and loss of function studies elucidated the anti-tumor effects of FAM201A on the regulation of proliferation, migration and invasion of NB cells." (PMID 37438449, 2023). "In the present study, we showed that FAM201A was down-regulated in NB cell lines and clinical tumor tissue samples, and closely associated with proliferation and metastases of NB cells, indicating its putative role as an anti-oncogene." (PMID 37438449, 2023). "Intriguingly, we identified the ability of FAM201A to encode the tumor-suppressing protein, NBASP, which interacted with FABP5 and negatively regulated its expression." (PMID 37438449, 2023). "In conclusion, our findings demonstrated that NBASP encoded by FAM201A played a tumor-suppressor role in NB carcinogenesis via down-regulating FABP5 to inactivate the MAPK pathway." (PMID 37438449, 2023). "Overall, ORF1 was the essential element of FAM201A, and it encoded NBASP functioned as tumor suppressor." (PMID 37438449, 2023). "In contrast, in our study, we discovered that FAM201A was down-regulated in NB tissues, and we therefore showed the tumor suppressor role in NB." (PMID 37438449, 2023). "The specific tumor-promoting role of FAM201A was illustrated in previous studies, which reported that knocking down FAM201A led to significantly suppressed proliferation, migration, and invasion of TNBC or LSCC cells." (PMID 36226250, 2022). "In vivo, when compared with control groups, FAM201A knockdown significantly blocked xenograft tumor growth (decreased tumor volume and weight), which confirmed that siFAM201A was able enhance radiosensitivity." (PMID 30574162, 2018). "FAM201A was upregulated in radioresistant ESCC tumor tissues and had a poorer short-term response to radiotherapy resulting in inferior overall survival." (PMID 30574162, 2018). "Overall, these results verified the anti-tumor role of FAM201A in NB cells." (PMID 37438449, 2023). "Moreover the knockdown of FAM201A in a xenograft tumor mouse model significantly blocked tumor growth with decreased tumor volume and weight, indicating that FAM201A could induce radiosensitivity both in vitro and in vivo in the model system." (PMID 32947897, 2020). "When compared with the control groups, FAM201A knockdown (sh-FAM201A) significantly blocked tumor growth (decreased tumor volume and weight), suggesting that the silenced FAM201A expression enhanced radiosensitivity, thereby confirming that FAM201A could induce radiosensitivity in vivo." (PMID 30574162, 2018). "To further characterize the anti-tumor potential effects of FAM201A, we used CRISPR Cas9 to knockout the endogenous levels of FAM201A in SK-N-SH cells, which had highest FAM201A expression." (PMID 37438449, 2023). "Compared with the lncRNA DLX6-AS1, FAM201A, and CASC2 yielded a superior AUC with specificity and sensitivity for distinguishing radiosensitive ESCC tumor tissues from radioresistant ESCC tumor tissues." (PMID 30574162, 2018). "Together, these results indicated that over-expressed ORF1 resulted in proliferation and metastasis suppression, similar to FAM201A itself on NB cell lines and ORF1 could restore the role of FAM201A knockout in promoting tumor." (PMID 37438449, 2023). "The Q-PCR results showed that FAM201A was reduced in NB tumor tissues, when compared with non-tumor samples." (PMID 37438449, 2023). "In the present study, we identified that the lncRNA FAM201A contributed the most to the radioresistance of ESCC regardless of the tumor stage." (PMID 30574162, 2018). "Tumor tissues from the remaining 35 enrolled patients (20 radiosensitive patients and 15 radioresistant patients, respectively) were collected to detect the expression of the lncRNAs CASC2, FAM201A, DLEU2, DLX6-AS1, and MCF2L-AS1 by RT-qPCR." (PMID 30574162, 2018). "However, neither high or low FAM201A expression was correlated with tumor stage, regardless of whether it was T or N stage." (PMID 30574162, 2018).
FAM201A also shares sentences with these, for which no sentence is quoted: triple-negative breast carcinoma (2 papers); endocervical adenocarcinoma (1); obsessive-compulsive disorder (1); Tourette syndrome (1).